GADL1 (GAD like acidic amino acid decarboxylase 1)
Description:
May catalyze the decarboxylation of L-aspartate, 3-sulfino-L-alanine (cysteine sulfinic acid), and L-cysteate to beta-alanine, hypotaurine and taurine, respectively. Does not exhibit any decarboxylation activity toward glutamate.
Synonyms: ADC; HuADC; CSADC; HuCSADC
Tractability: Antibody: the Human Protein Atlas places it where antibodies can reach.
Gene: Protein-coding gene on chromosome 3 (30,726,197 to 30,894,761, reverse strand). Ensembl gene ENSG00000144644.
Subcellular location (Human Protein Atlas): Cytosol; Plasma membrane
Pathways (Reactome):
Metabolism: Aspartate and asparagine metabolism; Degradation of cysteine and homocysteine
Gene Ontology:
Molecular function: aspartate 1-decarboxylase activity; sulfinoalanine decarboxylase activity; carboxy-lyase activity; carbon-carbon lyase activity; pyridoxal phosphate binding
Cellular component: cytoplasm; cytosol
Genetic constraint (gnomAD): Loss-of-function variants: 25 observed, 28.11 expected, observed/expected ratio (o/e) 0.89, 90% interval 0.65 to 1.24. The upper end of that interval is the gene's LOEUF score, 1.24, which puts it in group 5 of 6, group 1 being the genes least tolerant of losing a copy. Missense variants: 415 observed, 357.96 expected, observed/expected ratio (o/e) 1.16, 90% interval 1.07 to 1.26. Synonymous variants: 138 observed, 123.79 expected, observed/expected ratio (o/e) 1.11, 90% interval 0.97 to 1.28.
Homologues: Orthologues: chimpanzee GADL1 (99% identical), macaque GADL1 (98% identical), dog GADL1 (94% identical), rabbit GADL1 (93% identical), pig GADL1 (92% identical), guinea pig GADL1 (90% identical), rat Gadl1 (88% identical), mouse Gadl1 (87% identical), tropical clawed frog gadl1 (77% identical), Caenorhabditis elegans tdc-1 (20% identical), Drosophila melanogaster Tdc2 (19% identical). Paralogues in human: CSAD (57% identical), GAD1 (48% identical), GAD2 (47% identical), HDC (20% identical), DDC (19% identical), SGPL1 (17% identical), PDXDC1 (15% identical).
Diseases named in the same sentence as GADL1 in open-access papers:
GADL1 is named in the same sentence as 16 diseases in open-access papers, as found by Europe PMC text mining. Sharing a sentence is not in itself a finding about the gene and the disease. The quoted sentences say what the papers report.
bipolar disorder (4 papers, 2019 to 2020). A disorder of the brain that causes unusual shifts in mood, energy, activity levels and the ability to carry out day-to-day tasks. "In bipolar disorder (BD), the SNP rs17026688 in the gene encoding glutamate decarboxylase-like protein 1 (GADL1) has been associated with the response to lithium in Chinese patients." (PMID 32499729, 2020). "The level of GADL1 expression could affect cell migration, indicating that GADL1 might play an important role in the disease development of bipolar disorder." (PMID 30923325, 2019). "Besides, we found that BPI patients secreted higher amounts of GADL1 than healthy controls in the plasma, suggesting that GADL1 might play a role in the development of bipolar disorder in the Han Chinese population." (PMID 31311980, 2019). "Together, these results suggest that cell migration and related morphological changes might provide good indicators of the sensitivity toward lithium treatment, and the GADL1 stable overexpression cell line might serve as a useful platform to screen novel therapeutics for bipolar disorder." (PMID 30923325, 2019).
Anxiety (2 papers, 2020). Intense feelings of nervousness, tension, or panic often arise in response to interpersonal stresses. "The behavioral data in the Gadl1−/− mice suggest that the link between GADL1 with anxiety is worth exploring further, including the investigation of differences in sensory processing and alterations in fear-related behavior." (PMID 32733999, 2020). "Gadl1−/− mice also exhibited decreased anxiety, increased levels of oxidative stress markers, alterations in energy and lipid metabolism, and age-related changes." (PMID 32733999, 2020). "On this basis, it seems that a reduction of carnosine content in the mouse OB (~70%) and cerebral cortex (~40%) may result in the Gadl1−/− mice showing increased initiation to enter an exposed area (which is indicative of decreased anxiety)." (PMID 32733999, 2020).
bipolar I disorder (2 papers, 2015 to 2019). A bipolar disorder that is characterized by at least one manic or mixed episode. "The single-nucleotide polymorphism rs17026688 in GADL1 has been shown to be associated with lithium response in bipolar I disorder (BDI) patients of Han Chinese descent." (PMID 31767892, 2019). "The single-nucleotide polymorphism rs17026688 in the gene encoding glutamate decarboxylase–like protein 1 (GADL1) has been found to be associated with lithium response in Han Chinese patients with bipolar I disorder (BDI)." (PMID 31767892, 2019). "The two single-nucleotide polymorphisms (SNPs), rs17026688 and rs17026651, and the GADL1 variant IVS8 + 48delG are useful markers to predict the response to lithium treatment of patients of Asian descent who have bipolar I disorder." (PMID 25666066, 2015). "A link between genetic variations in the gene encoding glutamate decarboxylase-like protein 1 (GADL1) and response to lithium maintenance treatment for bipolar I disorder has been found in patients of Han Chinese descent." (PMID 25666066, 2015).
neuroblastoma (2 papers, 2019). Neuroblastoma (NB) is the most common solid, extracranial childhood tumor. "In this study, we assessed GADL1 function using a neuroblastoma cell line that stably overexpressed GADL1." (PMID 30923325, 2019). "Furthermore, we addressed for the first time the effects of lithium and GADL1 on the regulation of KCTD12 expression in human neuroblastoma cells." (PMID 31311980, 2019). "We hypothesized that lithium or GADL1 could regulate KCTD12 expression, and herein investigated the mechanism underlying the regulation of KCTD12 expression by lithium and GADL1 in the human neuroblastoma cells, SH-SY5Y." (PMID 31311980, 2019). "Our present study also demonstrated for the first time the relationships among lithium, GADL1, and KCTD12 in human neuroblastoma cells." (PMID 31311980, 2019). "In this study, we addressed how lithium and GADL1 influenced the activity of GSK-3, which regulated the expression of KCTD12 using the GADL1 stable overexpression neuroblastoma cell line." (PMID 31311980, 2019). "To test if GADL1 could affect GSK-3 activity, we established a cell clone that stably overexpressed GADL1 using SH-SY5Y neuroblastoma cells." (PMID 31311980, 2019).
amyotrophic lateral sclerosis (1 paper, 2020). Amyotrophic lateral sclerosis (ALS) is a neurodegenerative disease characterized by progressive muscular paralysis reflecting degeneration of motor neurons in the primary motor cortex, corticospinal tracts, brainstem and spinal cord. "Although baseline GADL1 levels are low, the levels of this enzyme may be up-regulated in response to oxidative damage and other physiological stressors, as shown in oligodendrocytes obtained from a mouse model of amyotrophic lateral sclerosis and in SKM upon exercise." (PMID 32733999, 2020).
eating disorder (1 paper, 2020). A broad group of psychological disorders with abnormal eating behaviors leading to physiological effects from overeating or insufficient food intake. "GWA studies (GWASs) have shown associations of the GADL1 locus with multiple human traits and diseases, including eating disorders, kidney functions, and several blood metabolites." (PMID 32733999, 2020).
glioblastoma (1 paper, 2022). The most malignant astrocytic tumor (WHO grade IV). "Two further enzymes that could be connected to changing hypotaurine levels were either not part of our RNA data set (glutamate decarboxylase like 1 [GADL1]) or only slightly increased in the IDH1-mut but not in IDH1-WT glioblastoma group (cysteine sulfinic acid decarboxylase [CSAD])." (PMID 34941573, 2022).
prostate carcinoma (1 paper, 2021). A carcinoma that arises from epithelial cells of the prostate gland. "The downregulation of COL4A6 was associated with prostate cancer progression and metastasis, and the overexpression of GADL1 was associated with cancer cell migration and morphology (including cell area, thickness, volume, perimeter length, irregularity, and eccentricity)." (PMID 34445498, 2021).
cancer (3 papers, 2021 to 2023). A tumor composed of atypical neoplastic, often pleomorphic cells that invade other tissues. "The expression of COL4A6 and GADL1 may be regulated by alternative splicing-coupled NMD to promote the development of cancer." (PMID 34445498, 2021).
GADL1 also shares sentences with these, for which no sentence is quoted: ovarian carcinoma (2 papers); ependymoma (1); immune dysfunction (1); ischemia (1); neuropathy (1); psychiatric disorder (1); tumor (1).